RORA (RAR related orphan receptor A)
Diseases named in the same sentence as RORA in open-access papers (continued):
Sharing a sentence is not in itself a finding about the gene and the disease.
lung carcinoma (11 papers, 2017 to 2024). "TIMELESS was significantly upregulated in lung tissue of clinical lung cancer patients as well as TCGA and Oncomine databases, while RORA was downregulated." (PMID 35078435, 2022). "Previous studies showed that circadian rhythm-related factors such as the ARNTL, CLOCK, RORA, RORB, CRY1, CRY2, and PER3 genes were associated with a higher risk of lung cancer." (PMID 36385012, 2022). "Collectively, lung cancer patients with high expression of TIMELESS or low expression of RORA, PER1, PER2, or CRY2 had a significantly poorer prognosis in OS." (PMID 35078435, 2022). "As result, we identified five target genes of metformin (RPS6KA5, RORA, SH3BP5, NUPR1, and CD40LG), which were significantly correlated with favorable prognosis and immune infiltration in lung cancer patients." (PMID 39135791, 2024). "The bioinformatics analysis identified five favorable prognostic MTGs (RPS6KA5, RORA, SH3BP5, NUPR1, and CD40LG) for NSCLC patients, all of which was downregulated in lung cancer tissues as compared with normal tissues." (PMID 39135791, 2024). "The log-rank test indicated a significant association of mRNA levels with overall survival (OS) of lung cancer patients (P < 0.05), and the TIMELESS, RORA, PER2, and CRY2 expressions were significantly correlated with progression-free survival (PFS) in lung cancer patients (P < 0.05)." (PMID 35078435, 2022).
cardiac hypertrophy (10 papers, 2020 to 2025). "Recently, we showed that global deficiency of the nuclear receptor RORα in the “staggerer” mouse exacerbates angiotensin II–induced cardiac hypertrophy and compromises cardiomyocyte mitochondrial function." (PMID 34756888, 2021). "Furthermore, there was more aggravated myocardial hypertrophy in RORα-deficient mice than in WT mice with Ang II continuous perfusion for 2 weeks." (PMID 36834872, 2023). "Furthermore, MnSOD over-expression attenuated myocardial hypertrophy in RORα-deficient mice, while knocking down MnSOD blunted the preventive effect against myocardial hypertrophy." (PMID 36834872, 2023). "Moreover, RORα-deficient mice exhibited more serious myocardial hypertrophy and worse cardiac function during the development of diabetic cardiomyopathy, which may be attributed to apoptosis augment, autophagy dysfunction, and oxidative stress enhancement." (PMID 36834872, 2023). "Cardiac hypertrophy is also mediated by MaR1 via RORα through the phosphoinositide 3-kinase (PI3K)/Akt signaling pathway and through the upregulation of IGF-1." (PMID 39518891, 2024). "Our previous work demonstrated that RORα mitigated Ang II-induced cardiac hypertrophy through the regulation of cardiomyocyte IL6 and STAT3 signaling." (PMID 34756888, 2021). "An increasing body of evidence suggests that retinoic acid-related orphan receptor-α (RORα) protects against Ang-II-mediated cardiac hypertrophy." (PMID 33259334, 2020). "Additionally, RORα has also been shown to protect against cardiac hypertrophy and heart failure induced by the renin–angiotensin–aldosterone system (ANG II)." (PMID 39518891, 2024). "Further study found that RORα agonist combined with RORα response elements in the promoter of manganese-dependent superoxide dismutase (MnSOD) induces MnSOD transactivation and thus combats myocardial hypertrophy." (PMID 36834872, 2023). "However, induction of RORα in the ANG II hearts was found to prevent cardiac hypertrophy." (PMID 39518891, 2024). "Further research confirmed that RORα function deficiency elevated interleukin 6 (IL-6) expression, promoted STAT3 activation, deteriorated mitochondrial function, aggravated oxidative stress, decreased total cardiomyocyte number, and finally exacerbated Ang II-induced myocardial hypertrophy." (PMID 36834872, 2023). "In addition, melatonin ameliorates oxidative stress during cardiac hypertrophy and cardio/cerebral ischemia-reperfusion in a RORα-dependent manner, with beneficial effects on pathological cardiac hypertrophy, myocardial infarction, ischemic stroke, and diabetic cardiomyopathy." (PMID 34064466, 2021). "Moreover, RORα and RORβ, nuclear MLT receptors, are involved in MLT-mediated regulation of pathological and physiological cardiac hypertrophy." (PMID 34899707, 2021).
colitis (10 papers, 2016 to 2025). Inflammation of the colon. "Using mouse models of EAE and colitis we show that loss of RORα affected the expression of IL-17A, RORγt, as well as the frequency of CD25+Foxp3+ Tregs in vivo." (PMID 33397953, 2021). "We next assessed whether loss of RORα affects the development of colitis, another chronic inflammatory disorder associated with increased TH17 differentiation and function." (PMID 33397953, 2021). "In mice with an intestinal epithelial-specific Rorα knockout, colitis is exacerbated, as Rorα suppresses the NF-κB-mediated pro-inflammatory activity." (PMID 40613788, 2025). "Mice with DSS-induced colitis exhibited notable reductions in Cry1, Per2, Npas2, and Rev-erbα expression, alongside significantly increased expression of Rorα." (PMID 40613788, 2025). "Examination of C57BL/6 mice with DSS-induced colitis revealed significantly reduced Cry1, Per2, Npas2 and Rev-erbα expression, but significantly increased expression of Rorα." (PMID 37218867, 2023). "Rodents with artificially induced colitis displayed decreased Per2, Cry1, Rev-erbα, and Npas2 levels and increased Rorα in colon tissue." (PMID 38089624, 2023). "7-DHC is a circadian amplitude enhancer, alleviating colitis in two ways that are intertwined: direct activation of RORα/γ and restoration of the circadian rhythm." (PMID 39872859, 2023). "Overall, 7-DHC ameliorates experimental colitis through RORα/γ activation and circadian restoration." (PMID 39872859, 2023). "In the intestinal epithelial cell, RORα attenuates NF-kB activity and inhibits excessive inflammation in a mouse colitis model." (PMID 35309302, 2022). "In mice with an intestinal epithelial-specific knockout of Rorα DSS-induced colitis is also increased." (PMID 35223537, 2022). "Recent studies have shown that disrupting genetic components of the circadian clock mechanism including the genes Per1/2, Nr1d1, and Rorα result in increased colitis severity." (PMID 35223537, 2022). "Here we show that RORα is a critical factor required for the development of autoimmunity and chronic inflammatory responses using mouse models of multiple sclerosis and colitis." (PMID 33397953, 2021). "Furthermore, an inverse agonist of RORα was shown to effectively alleviate autoimmune encephalomyelitis and colitis in mice." (PMID 40895530, 2025). "Mice lacking Rorα or Bmal1-driven Lnc-UC (a long noncoding RNA that is associated with colitis, particularly by reducing Rev-erbα expression) are more likely to have colitis than the control group." (PMID 38089624, 2023). "Furthermore, 7-DHC significantly increased the expression of RORα/γ target genes in the colon of jet-lagged mice with colitis, suggesting that targeting RORα/γ by 7-DHC reversed circadian dysregulation in colitis." (PMID 39872859, 2023). "Therefore, it was found that RORα is necessary to recover from colitis and maintain a functional intestine by reducing NF-κB transcription." (PMID 37218867, 2023). "Studies have also found that dietary supplementation with 400 ppm APS can significantly reduce IL-17 levels and RORα expression in the colon of mice with TNBS-induced colitis and increase the proportion of Treg cells in the colon, consistent with the results of this study." (PMID 35265068, 2022). "Based on the increased frequencies of Tregs in RORα-deficient mice with EAE and colitis, this molecular antagonism might occur at sites with different inflammatory stimuli than in the skin." (PMID 33397953, 2021). "Mice lacking Rorα or Bmal1-driven Lnc-UC were more susceptible to colitis than their control group." (PMID 37218867, 2023). "However, these genes are redundant in terms of clock function, hence the colitis phenotypes of the mutants are most likely attributable to Nr1d1 and Rorα function rather than a result of circadian rhythm loss which persists in the mouse strains used in these studies." (PMID 35223537, 2022).
colitis (continued). "Here the authors show that RORα is important in Th17 differentiation and that RORα deletion or a small molecule inhibitor of RORα can reduce disease in EAE and colitis mouse models." (PMID 33397953, 2021). "T-cell-specific deletion of RORα reduces the development of experimental autoimmune encephalomyelitis (EAE) and colitis." (PMID 33397953, 2021).
metabolic syndrome (10 papers, 2013 to 2022). A cluster of metabolic risk factors for CARDIOVASCULAR DISEASES and TYPE 2 DIABETES MELLITUS. "Decreased RORα expression in the mice was also associated with reduced inflammation in models of metabolic syndrome." (PMID 28744254, 2017). "RORα-deficient (staggerer) mice were shown to be protected against high fat diet (HFD)-induced metabolic syndrome as indicated by reduced weight gain, adiposity and hepatic steatosis, and improved insulin sensitivity." (PMID 26878025, 2015). "Retinoic acid-related orphan receptors RORα and RORγ play a regulatory role in lipid/glucose homeostasis and various immune functions, and have been implicated in metabolic syndrome and several inflammatory diseases." (PMID 23355833, 2013). "Regarding rs28571848, this SNP is linked to RORA, a nuclear receptor that has been found to participate in pre-adipocyte commitment, white adipose tissue inflammation in mice and metabolic impairments in humans with the metabolic syndrome." (PMID 33675863, 2021). "Indeed, the RORA-deficient staggerer mice exhibited severe dyslipidemia with high triglyceride concentration and low HDL-C level." (PMID 27556492, 2016). "Study of Staggerer (RORαsg/sg) mice, a natural mutant strain containing a deletion in the RORα gene that results in loss of RORα expression, indicated that RORα plays a critical role in the control of lipid metabolism and the development of various aspects of metabolic syndrome." (PMID 23355833, 2013). "Nobiletin (a natural flavone)-mediated activation of RORα/γ protects against metabolic syndrome, suggesting a role in metabolic regulation." (PMID 34183658, 2021). "Partial deletion of RORα protects against diet- and age-induced metabolic syndromes and inflammation." (PMID 28744254, 2017). "This RORα floxed model will provide a new tool to study the role of RORα in metabolic syndrome." (PMID 28744254, 2017).
neuroblastoma (10 papers, 2011 to 2025). Neuroblastoma (NB) is the most common solid, extracranial childhood tumor. "Our results showed that RORβ is highly expressed in the SH-SY5Y neuroblastoma cell line, compared to RORα and RORγ isoforms." (PMID 39105871, 2025). "For example, in human neuroblastoma, MYC amplification distorts circadian repressors (NR1D1) and circadian activators (RORA and BMAL1) to cause metabolic rewiring that fuels cancer cell growth and promotes poor patient outcomes." (PMID 37262074, 2023). "Additionally, as retinoic acid exerts its differentiation-stimulating effects through ROR2 and RORa in cultured mouse hippocampal neurons and neuroblastoma cell lines, we examined the roles of both RORa and ROR2 receptors in NME1-promoted neurite growth." (PMID 34623600, 2022). "Notably, we found that RORα expression predicts outcome independently of current prognostic factors, including age at diagnosis, International Neuroblastoma Staging System (INSS) stage, and MYCN status." (PMID 34183658, 2021). "Human neuroblastoma cells were transfected with a pSG5.HA vector containing the DNA-binding and transactivation sequence of RORA (pSG5.HA-RORA), and qRT-PCR analyses were performed to determine the amount of RORA and aromatase transcripts in the transfected cells 24 hrs after transfection." (PMID 21359227, 2011). "SR1078 can upregulate and activate RORα, restore the expression and activation of BMAL1, effectively block MYCN-mediated tumor growth, and enhance the sensitivity of neuroblastoma to chemotherapy." (PMID 41425709, 2025). "Human SH-SY5Y neuroblastoma cells over-expressing NPSR1 were stimulated with 100 nM NPS for 0–24 h and the mRNA expression of RORA was measured using real-time PCR." (PMID 23565190, 2013).
Sepsis (10 papers, 2021 to 2026). Sepsis is defined as life-threatening organ dysfunction caused by a dysregulated host response to infection. "Across eight independent GEO datasets, RORA expression exhibited a consistent downregulation trend in sepsis with high diagnostic value." (PMID 42096424, 2026). "Even more convincingly, a genome-wide association study in 28 human intensive care patients with sepsis identified blood leukocyte RORa as under-expressed and delayed in restoration, in high-severity versus low-scoring sepsis patients." (PMID 35169890, 2022). "Weighted gene co-expression network analysis was used to identify gene modules significantly associated with pediatric sepsis, and 237 high-confidence biomarkers were screened based on 14 machine learning models, among which RORA and GPR183 stood out in multiple models." (PMID 42023222, 2026). "Bioinformatics analysis identified RORA as a hub gene linking sepsis, cholinesterase, and immune responses." (PMID 42096424, 2026). "Subsequently, by integrating sepsis transcriptome data with cholinergic anti-inflammatory pathways and immune-related gene sets, we identified the hub gene RORA and validated it across multiple dimensions using public databases." (PMID 42096424, 2026). "This not only provides a new direction for understanding immune dysregulation in sepsis but also lays a theoretical foundation for the future development of RORA-targeted immunomodulation and treatment strategies for sepsis." (PMID 42096424, 2026). "For the first time, through multiomics integration and experimental validation, RORA has been identified as the key molecular bridge linking the cholinesterase activity and immunosuppression in sepsis." (PMID 42096424, 2026). "A total of six hub genes (RORA, L3MBTL2, PHC1, RPA1, CHD3, and RANGAP1) associated with SUMOylation was identified in sepsis in the current study." (PMID 40274894, 2025). "A significant difference in oxylipin profiles was noted in sepsis heart after treatment with melatonin and RORα delivery, while the difference was minor when using melatonin monotherapy." (PMID 37147703, 2023). "Our findings emphasized that a clinically safe dose of melatonin alone had limited cardiac benefits under severe sepsis, and the indispensable role of RORα in melatonin therapy should be considered in the clinic." (PMID 37147703, 2023). "Cardiac RORα delivery via UTMD/CMBs system strikingly optimized the antioxidative effect of melatonin in rats with fatal sepsis beyond a safe dose of melatonin alone." (PMID 37147703, 2023). "This is further corroborated by a gene and network analysis study performed in public data of paediatric sepsis patients, identifying RORa as one of fifteen master regulators that influence sepsis severity." (PMID 35169890, 2022). "RORA regulates genes in the circadian cycle, and a healthy circadian cycle positively impacts sepsis survival rate." (PMID 34680414, 2021). "The first cluster corresponded to TFs with decreased activity in pediatric sepsis, and GATA3 and RORA, as well as other TFs previously implicated in the context of inflammatory response." (PMID 34680414, 2021). "Finally, in the CLP sepsis mouse model, we measured cholinesterase activity and specifically quantified RORA mRNA expression in the spleen." (PMID 42096424, 2026). "Furthermore, previous studies have experimentally validated RORA as a potential key regulator in sepsis, as well as an immune dysregulation-related gene." (PMID 40274894, 2025). "Given the favorable biocompatibility, safety profile, and delivery efficiency of UTMD technology, the combined therapeutic approach of melatonin with RORα/cationic microbubbles may represent a promising strategy for managing sepsis-induced cardiomyopathy." (PMID 40959490, 2025). "Notably, in septic cardiomyopathy models, the UTMD-mediated cardiac delivery of RORα significantly enhanced melatonin's cardioprotective effects in sepsis." (PMID 40959490, 2025).